APP (amyloid beta precursor protein)
Diseases named in the same sentence as APP in open-access papers (continued):
Sharing a sentence is not in itself a finding about the gene and the disease.
Down syndrome (continued). "The observation that APPswe MC and other genetic groups with Aβ over-production, such as individuals with APP duplications and Down syndrome, do not appear to have increased Aβ concentrations in CSF has been reproducibly shown but is, to our knowledge, still unexplained." (PMID 39322953, 2024). "In patients with translocation Down'’ syndrome, the presence or absence of the APP gene in the translocation region determines whether the patient will eventually develop an AD phenotype." (PMID 38245771, 2024). "Furthermore, people with three chromosomes 21 copies, i.e., 21 trisomies and Down’s syndrome, developed AD neuropathology, but people with a partial 21 trisomy that did not include the APP gene did not develop AD neuropathology." (PMID 32183332, 2020). "In addition, the AD-related endosome dysfunction in Down syndrome was demonstrated to be independent of Abeta generation but to rely on the BACE1-catalyzed formation of the APP C-terminal fragment C99." (PMID 30853883, 2019). "The Down syndrome mouse was the Tc(Hsa21)1TybEmcf (Tc1) model, which carries a freely segregating chromosome 21 and is trisomic for 75% of the genes on this chromosome but, importantly, is not functionally triplicated for APP." (PMID 29945247, 2018). "However, consistent with previous studies in rats and Ts65Dn Down’s syndrome (DS) model mice, perinatal choline supplementation significantly upregulated dentate gyrus DCX staining and hippocampal DCX levels in both WT and APP.PS1 mice." (PMID 28103298, 2017). "However, recent findings in Tc1 mice that the final coding exon of APP is rearranged with no human APP protein detectable would argue that loci other than APP contribute to the sleep phenotypes in Down syndrome mutant models." (PMID 25558895, 2015).
memory impairment (248 papers, 2009 to 2026). "Instead, soluble amyloid processing products, including soluble Aβ oligomers 69, 70 and APP-βCTFs 71, 72, have been identified as the cause of synaptic damage and memory impairment." (PMID 40083942, 2025). "First, the AD pathology in the APP mice impairs plasticity producing associated learning and memory impairments in the HPC and related neural circuits that render the subjects less confident in finding the escape platform and so they remain near the pool wall." (PMID 37950055, 2023). "This was specifically demonstrated in mice in which the hepatocyte-restricted expression of the human mutant variant of APP displayed peripheral metabolism of Aβ peptides and associated neurovascular inflammation, CNS neurodegeneration, and memory impairment." (PMID 36824371, 2023). "Proband 1 (II:3) was a 53-year-old man, carrying the c.2061A > C (p.K687N) mutation in APP, who was initially admitted to our inpatient ward because of short-term memory impairment within 1 year." (PMID 37051054, 2023). "Specifically, animals with accelerated senescence exhibit higher levels of the amyloid-beta precursor protein (APP) and Aβ associated with learning and memory impairments at younger ages." (PMID 38254623, 2023). "Together, these results demonstrated that 6KApoEp therapy for 3 months wholly reduces spatial reference learning and memory impairment associated with the APP and PS1 transgenes." (PMID 37211092, 2023). "Animal models with human APP overexpression or APP familial mutations showed an increase in Aβ production and severe impairments in synaptic transmission associated with memory impairments." (PMID 35887159, 2022). "In this study, we demonstrated that the CpG methylation of the APP promoter by dCas9-Dnmt3a decreased the generation of neurotoxic Aβ peptides and improved AD-associated learning and memory impairment." (PMID 36109806, 2022). "This mouse model has five different FAD mutations in both amyloid precursor protein (APP) and presenilin, displaying higher levels of Aβ accelerating plaque formation and memory impairment." (PMID 34203049, 2021). "We also demonstrated that injecting SPON1 reduced the amount of Aβ and ameliorated cognitive dysfunction and memory impairment in 5xFAD mice expressing human APP and PSEN1 transgenes with five AD-linked mutations." (PMID 32455709, 2020). "Chakrabarty also reported that adeno-associated virus-mediated expression of IL-10 causes Aβ accumulation and memory impairment in APP mice." (PMID 31592103, 2019). "It has also been reported that synaptic disorders and dendritic dysplasia occur in the absence of Aβ amyloid deposition, and that C-terminal fragments of APP cause synaptic failure and memory impairment." (PMID 29440986, 2018). "We noticed that their memory impairment preceded Aβ accumulation and accompanied GABAergic depletion, which was presumably caused by the loss-of-function of APP." (PMID 28760161, 2017). "It’s plausible that by upregulating the levels of APP, and the production of Aβ consequently, the downregulation of let-7d is involved in learning and memory impairment caused by isoflurane." (PMID 25799420, 2015). "Given the slower development of remote memory impairment compared with recent memory loss in AD patients, APP/PS1 mice may serve as a more suitable model for investigating memory decline in AD." (PMID 41269883, 2025). "To investigate whether the memory impairments exhibited by APP/PS1 mice are linked to alterations in synaptic markers, we analyzed the total hippocampal protein expression, focusing on markers associated with learning and memory processes." (PMID 40004200, 2025). "Moreover, Aβ oligomer accumulation, NFT formation, and AD pathologies, such as synapse loss, neuronal loss, and memory impairment, were observed in double transgenic mice with APP E693del (Osaka) and human tau." (PMID 35214143, 2022).
memory impairment (continued). "We previously showed that the CLSPCOL-mediated restoration of the CLSP activity alleviated memory impairment, using a modified Morris water maze test, and improved neuronal synaptic loss, in APPswe/PS1dE9 double transgenic mice (APP/PS1 mice), at an advanced phase." (PMID 35178248, 2022). "In addition, long-term potentiation (LTP), a cellular surrogate for memory and memory impairment caused by extracellular Aβ and Tau oligomers are APP-dependent." (PMID 33172889, 2021). "To test whether PV interneuron hyperexcitability is causally involved in the observed memory impairment, we aimed to rescue memory by specifically reducing hippocampal PV interneuron activity in APP/PS1 mice." (PMID 31431685, 2020). "In conclusion, the present results provide the first evidence that isoflurane-induced learning and memory impairment in aged rats is associated with let-7d downregulation, which apparently increases expression of its target gene APP, consequently upregulating the expression of Aβ." (PMID 25799420, 2015). "Collectively, our findings suggest that APP mutations may contribute to early brain pathological changes and subsequent memory impairment in AD by downregulating membrane trafficking of FPN and inducing ferroptosis, thereby providing new molecular targets for drug development." (PMID 42123478, 2026). "Interestingly, in vivo and in vitro studies suggest that an excess of Zn can represent a risk factor for the development of AD, as it promotes APP expression, β-secretase cleavage, and Aβ deposition and aggravates tauopathy, resulting in learning and memory impairment." (PMID 36671042, 2023). "Meanwhile, overproducing APP fragments triggers typical Aβ pathology, neuroinflammation, and memory impairment in an age-dependent manner." (PMID 41164084, 2025). "In conclusion, our findings contribute to the understanding of progressive memory impairment in the APP mouse model." (PMID 41307180, 2025). "In this model, BACE1 elevation facilitated β-amyloidogenic processing of APP as measured by increased levels of β-CTF and the β-secretase-cleaved soluble ectodomain of APP (sAPP-β) and decreased sAPP-α, leading to aggravated learning and memory impairment." (PMID 41446639, 2025). "JNK inhibition, for example, was shown to eliminate memory impairment and long-term potentiation deficits in a mouse model of AD in which APP phosphorylation was inhibited." (PMID 38396891, 2024). "A recent study demonstrated that the ablation of senescent OPCs was sufficient to improve the memory impairment observed in the APP/PS1 model of AD." (PMID 38853911, 2024). "Memory impairments along with other AD pathologies including Aβ deposition, abnormal long-term potentiation appears between 3–6 months in APP/PS1 mice." (PMID 38956605, 2024). "The results indicated that NLRP1-siRNA treatment significantly alleviates the learning and memory impairments in APP/PS1 mice." (PMID 37055801, 2023). "APP NL-F mice recapitulate AD pathologies like Aβ pathology, neuroinflammation, and memory impairment, all occurring age-dependently." (PMID 37887303, 2023). "It was found that HLE markedly improved learning abilities and ameliorated memory impairment of APP/PS1 mice, as well as regulated antioxidant enzymes and bone metabolism proteins in mice serum." (PMID 36677642, 2023). "In the APP transgenic mouse model of AD, it has been shown that increased angiogenesis ameliorates memory impairment." (PMID 38275744, 2023). "In the Y maze test, the APP/PS1 mice demonstrated memory impairment with a significant (p < 0.01) reduction in number of arm entries compared to non-transgenic mice." (PMID 38111016, 2023). "Both APP and tau mouse AD models typically display disrupted spatially tuning in grid and place cells in conjunction with navigation or memory impairments." (PMID 37720546, 2023).
memory impairment (continued). "Altogether, the present study provides evidence that apicidin treatment ameliorated memory impairment in APP/PS1 mice, and this effect was attributed to decreasing the Aβ burden by promoting the expression of ADAM10." (PMID 36708130, 2023). "Nevertheless, the new model, APP/PS1/c-Abl KO mice, has significantly improved performance in all spatial memory tests, indicating that c-Abl absence attenuates AD-associated memory impairment." (PMID 37358955, 2023). "In another study, APPsw/o mice, that overexpressed human APP transgene, were exposed to Cu for 90 days, resulting in increased neuroinflammation, Aβ accumulation, memory impairment, and increased level of Cu in brain capillaries." (PMID 37887303, 2023). "In the RAWM test, the APP/PS1 mice showed signs of memory impairment as evidenced by significant increases in the numbers of errors in late retention trial T5 (p < 0.05 in block-1 and p < 0.001 in block-3) compared to non-transgenic mice." (PMID 38111016, 2023). "This suggests that chemical genetics triggers cascade activities including ACh transport, release, and synaptic transmission from the basal forebrain to the hippocampus, which can improve early memory impairment in APP/PS1 mice." (PMID 35418161, 2022). "For example, even before Aβ plaque deposition, depressive-like behavior and memory impairment are already present in male APP/PS1 mice." (PMID 35705972, 2022). "At the same time, treatment with GBLE significantly attenuated memory impairment of APP/PS1 mice as evidenced by increased number of crossing the original position of missing platform, elevated % distance and % time spent in the target quadrant." (PMID 36618950, 2022). "In the test trial, APP/PS1 mice showed memory impairment compared with the WT group suggested by decreased crossing times over the platform." (PMID 35286657, 2022). "Some researchers have noted that the targeted inhibition of Class I HDACs alters or even reverses memory impairment in transgenic mice in behavioral assays using the APP/PS1 mice injected with a systemic HDACI." (PMID 35807406, 2022). "Using the modified Morris water maze test, we previously showed that CLSPCOL rescued memory impairment in the 16-month-old APP/PS1 mice (advanced-phase AD model)." (PMID 35178248, 2022). "The lead compound 2c prevented scopolamine-induced spatial memory impairment and significantly reduced memory impairments in the APP/PS1 mice." (PMID 36431954, 2022). "At the same time, Aβ1–42/APP protein expression, which affects memory impairment, was reduced in the same groups when compared to the CON group." (PMID 35889329, 2022). "Our data demonstrated that ECH ameliorated memory impairments and decreased Aβ generation in APP/PS1 mice." (PMID 35665898, 2022). "Alteration in brain glucose uptake and its subsequent metabolism is a biomarker for memory impairment, and has been used to confirm the effects of Aβ-Teffs on the memory functions of APP/PS1 mice." (PMID 34798897, 2021). "As amyloid plaque develops by aggregation of soluble Aβ oligomers, which are toxic and contribute to memory impairment, we next assessed the expression of soluble human Aβ1–40 and Aβ1–42 levels in cortical brain tissues from APP/PS1 mice." (PMID 34798897, 2021). "The present study unveils the dynamics of protein farnesylation in the pathogenic process of human AD and provides novel insights into the specific impact of neuronal FT on AD-like memory impairment and amyloid pathology in APP/PS1 mice." (PMID 34315531, 2021). "In a triple transgenic mouse model (mutations in the APP, presenilin 1 (PSEN1) and TAU genes), the deletion of CB2 induces AD-like TAU pathology and memory impairment." (PMID 34001284, 2021). "Rosiglitazone reduced AD pathology and restored hippocampal function, leading to a rescue of memory impairment in APP transgenic mice." (PMID 34108878, 2021).
memory impairment (continued). "Beside memory impairments, it has been shown that the state of vigilance is reduced during AD-like pathology progression in APP/PS1 mice." (PMID 35173711, 2021). "Aβ-Th1 and Aβ-Th17 clones were adoptively transferred into APP/PS1 double-transgenic mice expressing chimeric mouse/human amyloid precursor protein and mutant human presenilin 1, and the mice were assessed for memory impairments." (PMID 34798897, 2021). "APP/PS1 mice showed signs of memory impairment evidenced by significant increases in the number of errors in late retention trial T5 (p < 0.05, block-1 and block-3) compared to non-Tg mice and were consistent with our previous reports." (PMID 34798897, 2021). "Withdrawal of treatment led to re-establishment of memory impairment assessed at 39 days after treatment suspension in old APP/PS1 mice." (PMID 32704089, 2021). "Untreated mice showed no preference toward the target quadrant, indicating a severe memory impairment, whereas indomethacin-treated APP/PS1 Tg mice exhibited improved behavior compared to untreated controls." (PMID 34360951, 2021). "Meanwhile, hyperexcitability of hippocampal PV interneurons is tightly correlated with memory impairment, and early intervention aimed at restoring PV interneuron activity rescues memory deficits and reduces amyloid plaque deposition in APP/PS1 mice." (PMID 35008611, 2021). "In our previous in vivo study, QKF was found to successfully ameliorate memory impairment and inhibit apoptosis in APP/PS1 double transgenic mice through its effects on the p38 MAPK pathway." (PMID 32831882, 2020). "These reductions in postsynaptic and presynaptic GABAB receptors likely contribute to the pathology and memory impairment described in the APP/PS1 model of AD, providing new insights to understand the pathological events taking place in the disease." (PMID 32252271, 2020). "Antisense oligonucleotides (ASOs) reducing tau expression have been able to protect against seizures in animal models, and were also able to revert memory impairments by reducing APP levels in the APP mouse model." (PMID 33297460, 2020). "We next investigated how early increased excitability of hippocampal PV interneurons in APP/PS1 mice correlates with memory impairment." (PMID 31431685, 2020). "In fact, studies have shown that a decrease in CCR2+ myeloid cells in APP/PS1 mice at 6 months of age was associated with increased levels of soluble oligomeric Aβ in the hippocampus and memory impairments." (PMID 31822279, 2019). "Daily intraperitoneal injection of this compound for 30 days was also able to rescue impaired hippocampal LTP and reduce memory impairment in the six-month old APP/PS1 mouse model of AD." (PMID 31882891, 2019). "In other APP Tg mice, for example APP-KI, 3xTg, and 5xFAD mice, memory impairments usually appeared at least 4 months of age or later." (PMID 31757975, 2019). "Reduced postsynaptic proteins were markers of APP/PS1 and APP/PS1/vehicle mouse groups were likely linked to memory impairments." (PMID 29729668, 2018). "APP/PS1 mice have been extensively used to better understand the pathogenic mechanisms underlying synaptic dysfunction and memory impairment in AD, and to screen new therapeutic approaches." (PMID 30107760, 2018). "The results suggested that EA at DU20 acupuncture had specificity of improve the learning and memory impairment in APP/PS1 transgenic mice." (PMID 29980225, 2018). "We found that blocking neurogenesis in the hippocampal DG prevented cohousing-induced rescue of memory impairment in APP/PS1 mice." (PMID 29325565, 2018). "Alterations in Nav1.1 channels along with inhibitory interneuron dysfunction culminating in hypersynchronous network activity and memory impairment was reported in AD mouse models overexpressing APP/Aβ." (PMID 28392767, 2017).